MT-TN (mitochondrially encoded tRNA-Asn (AAU/C))
Synonyms: trnN; formerly MTTN
Gene: Mitochondrial transfer RNA gene on chromosome MT (5,657 to 5,729, reverse strand). Ensembl gene ENSG00000210135.
Gene Ontology:
Molecular function: triplet codon-amino acid adaptor activity
Biological process: translation
Gene-disease validity (ClinGen):
ClinGen rates the evidence that MT-TN causes each of these diseases.
mitochondrial disease (mitochondrial): Definitive.